CASP1 (caspase 1)
Diseases named in the same sentence as CASP1 in open-access papers (continued):
Sharing a sentence is not in itself a finding about the gene and the disease.
infection (continued). "For example, mice lacking caspase 1 and infected with virulent E. japonica developed extensive liver damage, had a higher bacterial burden in the liver, and succumbed to fatal infection at earlier time points after infection when compared to similarly infected wild-type mice." (PMID 40488533, 2025). "MRC-5, MRC-9, and TIG-1 fibroblast cell death induced by live Mtb bacilli 2 days after infection was specifically inhibited by VX-765, an inhibitor of caspase-1/4, and MCC950, an inhibitor of NLRP3 inflammasome, but not by PAC-1, a caspase-3 inhibitor, and z-LEHD-fmk, a caspase-9 inhibitor." (PMID 40387341, 2025). "However, the influence of caspase 1 on CRIB cell-induced infection is not substantial, underscoring the necessity for further research to comprehend the mechanism of BoHV-1-induced inflammasome." (PMID 38590522, 2024). "Notably, the levels of activated caspase-1 and released IL-1β in response to LPS and ATP, which activate the NLRP3 inflammasome; dsDNA transfection and infection with F. novicida, both as activators of the AIM2 inflammasome, were reduced following transfection with Ncf1, Ncf2, or Ncf4 siRNAs." (PMID 38886341, 2024). "To determine whether absence of caspase-1 affected vaccine efficacy, we challenged mice with K. pneumoniae and evaluated bacterial burdens in the lungs and spleens 24 h post-infection." (PMID 38594380, 2024). "Moreover, in contrast to our observations in uninfected mice, whole colon lysates of C. rodentium-infected mice showed the presence of mature IL-18 as well as cleaved caspase-1 and GSDMD, indicating that this infection induced inflammasome activation in the colon." (PMID 38090573, 2023). "Simultaneous knockdown of caspase-1 and caspase-8 still allowed for the release of IL-18 during Δ6 Yptb infection, suggesting that they are unlikely to play overlapping roles and may act sequentially." (PMID 37615436, 2023). "The internalization of the parasites after 2 h of infection was not affected by the deficiency of GSDMD, NLRP3, or Caspase-1/11, but macrophages lacking any of these genes were more susceptible to intracellular replication of the parasite as observed after 48 h and 72 h of infection." (PMID 36828815, 2023). "Interestingly, by 72 h of infection, in the absence of Ch25h, there was a significant increase in Pycard and Casp1 gene expression observed." (PMID 36831236, 2023). "Indeed, while caspase 1 and 4 inhibitor Belnacasan marginally reduced the cell-to-cell transfer infection compared to that of DMSO, the pan-caspase inhibitor, QVD-OPH, markedly suppressed the cell-to-cell infections." (PMID 36780482, 2023). "The lack of effect of NLRP3 and Caspase 1/11 on host cell death during infections with ply+lytA+ strain A66 was unexpected, however receptor redundancy in macrophage death pathways may contribute to the lack of effect of the single knock-outs." (PMID 36897919, 2023). "As a protein complex composed of NLRP3, ASC, and caspase-1, NLRP3 inflammasome has the function of recognizing external stimuli and internal danger signals and initiating an inflammatory response, playing an important role in the induction of infection and autoimmune responses." (PMID 36691639, 2023). "To determine whether ExoU alone, in the absence of infection, was able to activate caspase-1 in PMVECs, we used an ectopic expression system to induce intracellular ExoU expression." (PMID 35202178, 2022). "Although we cannot exclude that lower bacterial loads in MRP8Cre+Casp1flox mice could influence the levels of IL-1β measured in BALFs, those results suggest that neutrophil Caspase-1 is also a contributor of IL-1β production upon PAO1, PAO1ΔExoS and PP34ExoUS142A infections." (PMID 35849616, 2022). "In contrast, caspase-1 cleavage could not be detected after infection with theP. aeruginosa strains PAO1ΔmucA/EV and PAO1ΔmucA/L012mucA." (PMID 36604139, 2022).
infection (continued). "Moreover, we also measured IFN-γ expression in the splenocytes and serum, as well as its production by T cells of WT or Casp1/11−/− mice with or without anti-IFNAR antibodies treatment post-PRU infection." (PMID 36214572, 2022). "For instance, upon infection of differentiated human nasal epithelial cells (hNECs) and primary human nasal epithelial progenitor cells with human rhinovirus (HRVs), the epithelial NLRP3 inflammasomes mediated the hNEC pyroptosis via DDX33/DDX58–NLRP3–caspase-1–GSDMD axis." (PMID 35806033, 2022). "The pattern of GASDMD expression approximated that of caspase-1, although we could not see the cleavage of this protein after 24 h of infection." (PMID 35765029, 2022). "However, caspase-1 was not activated significantly for the cleavage of caspase-1 p20 subunit by Ms_PE_PGRS19 infection." (PMID 36557726, 2022). "In addition, these cells are distinguished by increased expression of several HIV restriction factors, which further reinforces their nonpermissive state, encouraging abortive infection and caspase-1 dependent pyroptosis." (PMID 35784348, 2022). "Infection with S. typhimurium induced phosphorylation in NLRC4 at serine 533 which could not be prevented by CASP1 inhibition, clearly suggesting that this phosphorylation event occurred upstream of CASP1 cleavage." (PMID 34276697, 2021). "Infection with VACV deletion mutants ΔA49, ΔB13, and ΔB15, which lack molecules that inhibit NF-ĸB, caspase-1, and IL-1, respectively, did to provoke DC migration, revealing, at least, that deletion of these specific molecules from VACV could not rescue the migration phenotype observed in our model." (PMID 33419767, 2021). "Furthermore, SC79 treatment resulted in a significant decrease in caspase-1 (p10) and GSDMD-N levels during infection with the ΔSopB strain, indicating that Akt phosphorylation both delayed pyroptosis and aggravated the severity of pyroptosis of infected Caco-2 cells." (PMID 34804044, 2021). "Furthermore, compared with the HPI− group, the NLRP3 positive cell rate in the HPI+ group were significantly higher (P < 0.01) at 0.5, 6 and 9 h after infection, the caspase-1 positive cell rate in the HPI+ group were significantly higher (P < 0.01) at 3 and 6 h after infection." (PMID 33678162, 2021). "Astrocytes also had low levels of caspase-1 activity that did not increase with infection." (PMID 33524073, 2021). "Therefore, while caspase-1 likely does not play a major role in cell death during infection with clinical P. aeruginosa isolates from CF patients, canonical inflammasome activation appears to play a role in IL-1β maturation and secretion." (PMID 33664232, 2021). "In senescence-related susceptible individuals exposed to endogenous (genetics and epigenetics) stress and exogenous (environment and infection) injury, virus-induced NLRP3 inflammasome activation may drive the inflammation response by activating caspase-1 and production of mature IL-1β and IL-18." (PMID 34638790, 2021). "Interestingly, ILA did not reduce caspase-1 activation when macrophages were activated with Δcap67 infection instead of nigericin." (PMID 33380899, 2020). "Furthermore, the absence of Asc, Nlrp3/Aim2 or Casp1/11 had no impact on cell death upon infection with strains of M. tuberculosis, indicating that M. tuberculosis-induced cell death is inflammasome-independent." (PMID 32111888, 2020). "In addition to non-expression of inflammasome genes after 8 hours of infection, L. infantum neither activate caspase-1 nor determined IL-1β production in the three evaluated time-points, confirming that this platform was not indeed activated." (PMID 31961876, 2020). "Thus, we confirmed that the activation of Caspase-1/11 and Gsdmd was required for the SS2-induced IL-1β release and cytotoxicity in BMDMs ex vivo, and this activation contributes to mouse death and IL-1β release in response to the SS2 infection in vivo." (PMID 32922370, 2020).
infection (continued). "Our previous studies show that infection with either P. vivax or P. falciparum prime circulating monocytes to express an inflammasome gene signature, form AIM2, NLRP3, and NLRP12 specks, express active caspase-1, and produce high levels of IL-1β, when challenged with LPS18,19,32." (PMID 32929083, 2020). "We first analyzed peritoneal cells after the 3 days of in vivo infection, and established that there is an increase in FAM-YVAD-FMK probe reactivity in peritoneal cells of WT mice, as well as a decrease in PI incorporation in cells derived from Casp-1/11−/− mice." (PMID 32523898, 2020). "In addition, infection of platelets with DENV leads to the assembly of the NLRP3 inflammasome, activation of caspase-1, and the production of IL-1β, which is secreted in microparticles and can promote increased vascular permeability, a phenomenon associated with the severity of the disease." (PMID 30901375, 2019). "At 3 and 6 hours post infection, MAYV induced increased expression of Casp1, Nlrp3, Aim2 and Asc." (PMID 31479495, 2019). "In contrast, infection with Ad ΔVAI did not reduce the accumulation of secreted and proteolytically matured caspase-1 and IL-1ß, corroborating the hypothesis that VA RNAI is required for the suppression of inflammasome activity." (PMID 31849970, 2019). "Infection of human corneal epithelial cells with virulent HSV-1 strains (McKrae or 17) or with the clinical isolate KOS79 induced a significant increase of the FLICA straining, confirming the western blot data that Caspase-1 is highly activated in human corneal epithelial by virulent strains." (PMID 31367214, 2019). "After VSV or EMCV infection, despite NLRP3 inflammasome activation, cell death was not affected in NLRP3, ASC, or caspase-1-deficient BMDMs or after treatment with a broad caspase inhibitor like zVAD-fmk, suggesting that pyroptotic or apoptotic cell death was not involved." (PMID 31024004, 2019). "The cleaved/activated Caspase-1, cleaved/activated IL-1β, and IL-18 were significantly induced in human corneal epithelial cells following infection with virulent laboratory strains of HSV-1, McKrae and 17, as early as 2 h post-infection, compared to control β-actin (P < 0.05)." (PMID 31367214, 2019). "Notably, while at 6 h post infection cytotoxicity was slightly reduced in caspase-1/11−/− but not in caspase-11−/− macrophages, V. cholerae infection was equally cytotoxic to all genotypes at 24 h post infection." (PMID 31736941, 2019). "Therefore, in our study, the production of IFN-γ was reduced in serum but was not altered at the initial infection site of Nlrp3−/−, Asc−/−, and Caspase-1/11−/− mice when compared with WT mice during N. caninum infection." (PMID 30105037, 2018). "However, we did not detect cleavage and release of caspase-1 or activation of pyroptosis in T. gondii-infected cells even following LPS priming, suggesting that infection with these strains does not result in classical inflammasome activation." (PMID 30154263, 2018). "Moreover, that study used a strain of B. thailandensis that has been passaged into Casp1-/-/Casp11-/- mice to acquire higher virulence and used the intraperitoneal infection route, rather than the intranasal one, as in our study." (PMID 29791511, 2018). "The increases in IL-1α observed later during infection in the spleens of BALB/c mice could indicate activation and secretion of IL-1α by inflammasome activation, though further data, such as caspase-1 activation and IL-18 expression would be required to validate this hypothesis." (PMID 30500862, 2018). "However, CASP1 activation during G18 infection was not statistically significantly higher than that observed in uninfected bMDM due to the level of variation in the biological replicates, as with the IL-1β ELISA results." (PMID 29263113, 2018).
infection (continued). "Notably, an infection in primed macrophages was unable to activate caspase-1 or IL-1β and mice deficient in the key inflammasome components ASC and caspase-1/11 showed no change in their disease phenotype." (PMID 29487860, 2018). "In addition, we observed only a slight difference in cytotoxicity between the ΔspeB and wt strains after infection of B6 BMDMs, and the ability of these strains to induce cell death was independent of caspase-1." (PMID 28720729, 2017). "To determine whether AIM2 accounted for the restriction of bacterial replication in the absence of caspase-1/11, we compared infection of Aim2/Casp1/11-/- with Casp1/11-/-." (PMID 28771586, 2017). "Interestingly, infection with H. parasuis did not enhance the level of mRNA expression of ASC nor that of caspase-1 (p > 0.05)." (PMID 27502767, 2016). "However, it was unable to increase the larval infection resistance when expressed alone, even though it increased caspase-1 activity in non-infected animals." (PMID 27363812, 2016). "However, Gbp4ΔCARD promoted a dose-dependent caspase-1 activation in non-infected larvae, while inhibited its activation on infection." (PMID 27363812, 2016). "In consistence, both ΔYopM/YopM and ΔYopM/C68A infection failed to activate caspase-1 cleavage." (PMID 27929533, 2016). "Notably processing of caspase-1 was absent after infection of cells possibly due to the lack of inflammasome activation or complex formation." (PMID 26114647, 2015). "The NLRP3 inflammasome is known to be triggered by infection with A/E pathogens and shows a non-redundant role in caspase-1 activation when mouse macrophages (mBMDM) are challenged with Citrobacter rodentium, a mouse A/E pathogen possessing the nleA homologous gene." (PMID 26332984, 2015). "Neither pro-caspase-1 nor ASC showed any cleavage after infection." (PMID 26114647, 2015). "In contrast, SchuS4 infection did not induce cleavage of caspase-1 or secretion of IL-1β." (PMID 25191316, 2014). "Although the possible targets of caspase-1 and caspase-11 mobilized during pyroptosis remain unidentified, the studies involving NAIP/NLRC4 hugely contribute to the idea that this inflammatory form of cell death is an important effector mechanism against infections." (PMID 25071770, 2014). "In addition, mutants lacking FLT_0325 also induce higher levels of caspase-1 activation dependent on Aim2 and Tlr2 and secretion of IL-1β dependent on Tlr2, Aim2, and Nlrp3 in the early periods of infection." (PMID 24324933, 2013). "Given the unexpected observation that P2X4 can modulate ATP-dependent caspase-1 activation in the immortalized HIGK cells, we examined whether a similar effect could be observed in immortalized (HIGK) cells and primary GEC during infection with P. gingivalis." (PMID 23936165, 2013). "Furthermore, expression of hsp90 was persistent during the infection process and no dramatic difference was observed between normal and Sf-caspase-1-repressed cells." (PMID 23134743, 2012). "Furthermore, Mtb infection did not lead to an increase in cell membrane permeability after infection of wild-type and Casp1/11−/− BMDCs." (PMID 22911706, 2012). "However, MØ lacking caspase-1 (which is required for production of bioactive forms of these cytokines) also produced high amounts of IL-12p40 after infection with ΔROP16 parasites." (PMID 21931552, 2011). "Despite the fact that cell death involved plasma membrane permeabilization and coincided with IL-1β release, we conclude that necrosis induced upon infection of human macrophages with virulent Mtb secreting ESAT-6 over several days is independent of caspase-1 and cathepsin B." (PMID 21637850, 2011). "We recently demonstrated that upon infections and cell stress conditions, such as treatment of cells with bacterial RNA or heat killed gram positive and gram negative bacteria, ASC redistributes from the nucleus to the cytosol, where it aggregates with NLRs and caspase 1 into perinuclear structures." (PMID 20482797, 2010).
infection (continued). "However, at high MOI, L. pneumophila induced significant apoptosis within 2 hrs of infection in all macrophages except those lacking caspase-1." (PMID 19343209, 2009). "To rule out this explanation, we infected Casp1−/− macrophages, which are resistant to cell death at the early timepoints examined (e.g., 4h post infection), and asked whether type I interferon was still hyperinduced in response to ΔsdhA L. pneumophila." (PMID 19936053, 2009). "In addition, even infection of macrophages with the classical RIPK1/caspase-8–activating pathogen, Yersinia pseudotuberculosis, sensitized TBK1/IKKε-inhibited cells to enhance RIPK1/caspase-8 activation and death but also enhanced secondary caspase-1 activation." (PMID 40053580, 2025). "Comparatively, at the corresponding time points, we observed a reduction of caspase-1 cleavage in brains infected with 93/4286ΩhrpB after 24 and 48 h (by 84% ± 0.053 and 77,8% ± 0.017, respectively) compared to brains infected with 93/4286, while no changes were found after 12 h of infection." (PMID 39376663, 2024). "However, the addition of IL-1β, and/or IL-18 to macrophages at the time of infection did not suppress Legionella replication in Ipaf knockout macrophages, indicating that caspase-1 activation is critical for the clearance of the bacterium independently of the activity of IL-1β and IL-18." (PMID 39625520, 2024). "However, CASP8 siRNA knockdown in CASP1−/− Caco-2 cells did not abrogate inflammasome activation during Δ6 Yptb infection, indicating that additional caspase activation pathways likely mediate cell death during Δ6 Yptb infection of human IECs." (PMID 37615436, 2023). "Additionally, immunofluorescence staining using specific DBV Gc antibody and cleaved caspase-1 observed that DBV was widely distributed within caspase-1+ macrophagic niches and accumulated around the nucleus at 72 h post-infection, which might facilitate pyroptotic cell death of macrophages." (PMID 37486928, 2023). "However, in late infection, SVV may reduced caspase-1 expression because 3Cpro cleave NLRP3." (PMID 35958608, 2022). "We investigated whether infection with the P. aeruginosa strain, PAO1, induced expression of components of the NLRP3 inflammasome and found that a 6-h infection significantly increased expression of NLRP3, the adapter protein ASC, caspase-1, IL-1β, and IL-18 in BEAS-2B bronchial epithelial cells." (PMID 35215060, 2022). "However, the induction of pro-inflammatory mediators only functions to keep bacterial growth in check, as evident by heightened bacterial burdens in TLR2 and caspase-1 KO mice, but does not lead to infection clearance, since biofilms remain chronic in the WT setting where both molecules are present." (PMID 32290861, 2020). "Our work identifies a key role of caspase-1 (not -11) mediated IL-18 production, IL-18-mediated accumulation of mature natural killer (NK) cells in the mucosa and suggests that NK-cell perforin is important for mounting gut inflammation within 12h of the infection." (PMID 27341123, 2016). "However, iNOS−/−, NLRP3−/− and caspase-1−/− mice do not succumb to infection, unlike MyD88−/− mice." (PMID 24098823, 2013). "Notably, we observed the enhancement of IL-1β release after infection with a T3SS1 mutant expressing TdhA and S (ΔvcrD1), compared with that after infection with WT bacteria, raising the possibility that T3SS1 is involved in the inhibitory function in addition to triggering caspase-1 activation." (PMID 23357873, 2013). "Because NLRP3 activation leads to caspase-1 activation and consequent IL-1β secretion, we next asked whether caspase-1 and IL-1β are required for NLRP3-dependent NO production in response to T. cruzi infection, and what role these molecules play in the control of infection by macrophages." (PMID 24098823, 2013).